IL10 (interleukin 10)
Diseases named in the same sentence as IL10 in open-access papers (continued):
Sharing a sentence is not in itself a finding about the gene and the disease.
colitis (continued). "Some proinflammatory cytokines and mediators (e.g., TNF-a, IL-6 and IL-1β) have been used as markers of anti-inflammatory activity in a dextran sodium sulfate colitis mouse model, and IL-10 has anti-inflammatory properties and functions in immune regulation." (PMID 34490398, 2021). "MiR-31 expression also targets and inversely correlates IL-25, regulates IL-12/23-mediated Th1/Th17 inflammatory responses during the chronic inflammation process in TNBS-induced and IL-10 knockout colitis mice models." (PMID 33921348, 2021). "On the other hand, lower level of IL-10 was observed in DSS-induced experimental colitis in parallel to the control group." (PMID 33859564, 2021). "In mice, co-transfer of IL-10-producing CCR5+PD-1+ Tr1 cells strongly inhibits colitis induced by transfer of Th17 cells, whereas IL-10-producing control T cells lacking CCR5 and PD-1 are less efficient." (PMID 34421921, 2021). "Using a select CB2 agonist, JWH-133, it was shown that this compound attenuated chronic colitis in IL-10 (−/−) mice as well as in mice with dextran sodium sulfate (DSS)-induced colitis." (PMID 34298921, 2021). "The IL-10-positive monocytes effectively inhibited the proliferation of CD4+ effector T cells in vitro and the adoptive transfer of IL-10-primed monocytes into mice suppressed the inflammatory state in experimental colitis." (PMID 34476533, 2021). "It should also be noted that in preliminary studies we demonstrated that two independent consortia of 14 and 19 bacterial isolates, respectively, from two healthy human volunteers induced colitis when colonized into germ-free 129 Il10−/− mice." (PMID 34050144, 2021). "Patients with identified defects in Il-10 pathway manifest with severe colitis with perianal lesions which occurs within first months of life and is resistant to standard therapy." (PMID 33691712, 2021). "Gammaproteobacteria are reproducibly increased in patients with active IBD, and AIEC induce cecal-predominant colitis in monoassociated gnotobiotic 129 SvEv IL10−/−." (PMID 34684567, 2021). "In particular, the expression of miR-124 was found inversely correlate with STAT3 in both DSS-induced and IL-10 knockout colitis mice models and CRC patients, as well." (PMID 33921348, 2021). "FMT has previously been shown to promote the induction of anti-inflammatory properties via boosting IL-10 production in the context of a DSS-colitis mouse model." (PMID 33531483, 2021). "Overall, IL-10−/− animals with H. hepaticus-triggered colitis and infected with C. difficile had higher clinical disease scores than mice with IBD alone." (PMID 34126769, 2021). "Recent studies showed that IL-10 signals drive macrophages to express tolerogenic functions that prevent colitis." (PMID 34239502, 2021). "Therapeutic FMT administered during experimental colitis directly modulates mucosal immunity promoting IL10-dependent anti-inflammatory responses." (PMID 33549144, 2021). "Our results show that the concentration of the anti-inflammatory cytokine IL-10 at both time points was lower in colitis rats than in the control rats, with higher levels observed after 7 days." (PMID 33923129, 2021). "In a model of colitis, the administration of L. lactis Hsp65 prevented a reduction in IL-10 levels in colon tissue, which was shown to be critical to immunoregulation." (PMID 34248935, 2021). "SCFA produced by Clostridia of the Cluster IV, XIVa, and XVIII promote the accumulation of interleukin (IL)-10 producing regulatory T (Treg) cells in the colon and attenuate pathology in a colitis model." (PMID 34276696, 2021). "The proinflammatory cytokine levels of IL-1β, TNF-α, IL-6, and IFN-γ were increased whereas the anti-inflammatory cytokine IL-10 was decreased in colitis mice." (PMID 33995942, 2021).
colitis (continued). "Breg-like cells (IL-33 + Breg) isolated from mice with IBD inhibited the expansion and functioning of immune effector cells and effectively prevented the development of spontaneous colitis in IL-10 − / − mice after adoptive metastasis." (PMID 33462754, 2021). "In the IL-10 knockout model of spontaneous colitis, an increase in barrier permeability precedes the onset of disease." (PMID 34959809, 2021). "A bacterial polysaccharide of Bacteroides fragilis also induced IL-10 producing Treg cells, which protect against experimental colitis induced by Helicobacter hepaticus." (PMID 34276696, 2021). "Germ-free IL-10−/− mice colonized by the intestinal microbiota of IBD patients exhibit increased colitis as compared to mice colonized with the intestinal microbiota derived from healthy human controls." (PMID 34513862, 2021). "In the innate immune system, C. butyricum directly triggers IL-10 production by intestinal macrophages in inflamed mucosa, preventing colitis." (PMID 33451114, 2021). "Treatment with anti-CXCL10 antibodies attenuated colitis in IL10-deficient mice and in DSS colitis and reduced cell infiltration to the lamina propria." (PMID 34017333, 2021). "Since previous studies have shown a protective role for IL-33 in DSS-induced colitis, we compared Il33 induction in Il10−/− chronic colitis and DSS-induced acute colitis." (PMID 33953267, 2021). "On the other hand, this potential explanation does not explain the finding of unchanged colon Il33 expression during colitis in Il10−/− mice." (PMID 33953267, 2021). "Basic science studies have shown that Clostridium plays a role in regulation of the inflammatory response, and that IL-10 upregulation by Prevotella contributes to colitis onset and progression." (PMID 34215773, 2021). "Accordingly, we investigated the endogenous opioid-mediated regulation of peripheral inflammation and epithelial barrier integrity in IBD-like colitis in IL-10-/- mice." (PMID 34299013, 2021). "A different group further suggested that BM-derived mesenchymal stromal cells can secrete CCL2 and CXCL12, subsequently upregulating IL-10 expression in CCR2+ MPs in a model of chemically induced colitis." (PMID 34650568, 2021). "Various mouse models of colitis, including mice deficient in Muc2, Tlr5, Il10, or DSS-induced colitis model, had bacteria penetrating into the otherwise impenetrable inner colonic mucous layer." (PMID 34814945, 2021). "To determine the role of IL-33 in a spontaneous chronic model of colitis, we crossed Il10−/− mice to Il33−/− to generate Il10−/−Il33−/− mice." (PMID 33953267, 2021). "As a typical anti-inflammatory cytokine produced by various cells (i.e., B and T lymphocytes, macrophages, and dendritic cells) in IBD, IL-10 plays a central role in gut homeostasis and colitis prevention." (PMID 34421890, 2021). "IL-10 is a necessary inflammatory factor for inducement and maintenance of regulatory T (Treg) cells against colitis." (PMID 35059326, 2021). "The phenotype named Colitis contains seven DEGs from our lists: IL10, IL11, IL1B, IL1RN, IL6, MIF and TNF." (PMID 34680872, 2021). "Later studies showed that colitis in SPF housed Il10-/- mice required the presence of Helicobacter species." (PMID 34421921, 2021). "The authors again showed that long-term dietary supplementation with pineapple decreases colon inflammation and neoplasia in IL-10‒/‒mice with chronic colitis." (PMID 34959865, 2021). "This study investigated the differential abilities of CMC and P80 to induce or exacerbate experimental colitis in 8–12 week-old humanized IL10−/− 129SvEv mice." (PMID 34684567, 2021). "This is concordant with what is known about the role of IL-10 in the gut and its role in the prevention of colitis." (PMID 33717186, 2021). "SCFAs activate STAT3 and mTOR pathways in Th1 through GPR43 and up-regulates the expression of transcription factor Blimp1, thus promoting Th1 to produce IL-10 and alleviating the colitis of mice." (PMID 34884466, 2021).
colitis (continued). "It is well established that IL-10 secretion by Tregs is essential for preventing gut inflammation and colitis." (PMID 33351782, 2021). "Consistently, DSS-induced colitis rats exhibited upregulation of IL-17A and IL-6 and downregulation of IL-10 and TGF-β1 in the colonic tissues." (PMID 33722292, 2021). "IFNG-AS1 expression significantly increases in the intestinal mucosal tissues of IBD patients, 2,4,5-trinitrobenzenesulphonic acid- (TNBS-) induced colitis mouse models, and spontaneous colitis in IL-10 knockout mice." (PMID 34485536, 2021). "The IL-10 knockout mice develop spontaneously colitis on account of the intolerance to intestinal bacteria and microbiota-induced activation of effector T cells." (PMID 34386004, 2021). "At a 1% concentration, identical to the doses that we used, P80 and CMC were reported to have very similar abilities to induce colitis in conventional C57Bl/6 IL10−/− mice." (PMID 34684567, 2021). "In contrast, the rTsSp pre-treatment increased IL-10 expression in the colon tissues of mice with DSS induced colitis." (PMID 33995396, 2021). "Due to the impact of PTEN on important cell functions and TLR signaling, disruption of PTEN in the intestinal epithelium of IL-10(−/−) mice hastened the occurrence of severe colitis." (PMID 34140896, 2021). "IL-10 is an anti-inflammation cytokine involved in colitis progression, and it plays an essential role in the recovery of tissues." (PMID 35010997, 2021). "In their study, Il10−/− mice developed spontaneous colitis and presented feces with less OTUs and a lower Margalef richness index than the WT mice." (PMID 33578830, 2021). "As an important anti-inflammatory cytokine, IL-10 has been revealed to be decreased in numerous mouse models of colitis." (PMID 33995942, 2021). "Atopobium has been linked to mitochondrial dysfunction, and the transfer of Atopobium triggers colitis in IL10-/- mice." (PMID 34367134, 2021). "In particular, Kyna suppressed anti-inflammatory IL10 and contributed to colitis in mice, but attenuated the TNF-α expression in human mononuclear cells activated by heat-inactivated Staphylococcus aureus." (PMID 34948292, 2021). "Acetate, propionate, and butyrate enhance the phosphorylation of mTOR and STAT3 in Th1 cells, thereby promoting IL-10 production in Th1 cells and relieving colitis." (PMID 33505215, 2021). "In the case of the IL-10R deficiency-associated VEO-IBD, the investigation of iPSC-differentiated macrophages is of major importance as the dysfunction of IL-10 signaling in these innate immune cells directly leads to a severe form of colitis." (PMID 33804706, 2021). "The mRNA expression of IL-1β, IL-18, IL-6, TNF-α, IFN-γ, ICAM-1, and VCAM-1 was markedly (all p < 0.01) up-regulated in DSS-induced colitis group, while the IL-10 expression was significantly (p < 0.01) down-regulated." (PMID 33859564, 2021). "Our present study demonstrated that Wogonin extended the therapeutic efficiency of MSCs on DSS-induced murine colitis in vivo, which was due to the increased IL-10 expression in the intestinal tissue and peritoneal cavity." (PMID 34239686, 2021). "Oral administration of I3Pr was shown to improve DSS-induced murine colitis symptoms, which was attributed to increased signaling of the anti-inflammatory cytokine IL-10, due to higher expression of IL-10 receptors." (PMID 34073220, 2021). "Patients with identified defects in Il-10 pathway manifest with life-threating colitis with perianal lesions which occurs within first months of life." (PMID 33691712, 2021). "In our model of more aggressive experimental colitis in ex-GF 129SvEv IL10−/− mice humanized with pooled IBD fecal microbiota, CMC induced more active colitis than did P80 or water administration." (PMID 34684567, 2021).
colitis (continued). "F. prausnitzii A2-165 also exerted anti-inflammatory effects on both cellular and colitis animal models by blocking NF-KB activation and IL-8 production, facilitating the induction of IL-10 in human and murine dendritic cells and modulating T cell responses." (PMID 33641084, 2021). "IL-10 participates in suppressing the antigen presentations and the synthesis of pro-inflammatory cytokines in colitis." (PMID 34090510, 2021). "Clostridium species have been shown to suppress colitis via promoting the subsequent accumulation of IL-10-producing intestinal Treg cells and providing bacterial antigens and a TGF-β-rich environment to help the differentiation of Treg cells in mice." (PMID 33451114, 2021). "In particular, Th1 (producing IFN-γ), Th17 (producing IL-17A and IL-17F) and Treg (producing IL-10) have been reported to be associated with Crohn’s Disease in humans and DSS-induced colitis in mice." (PMID 34407839, 2021). "As the best-studied zwitterionic capsular polysaccharide, polysaccharide A has been confirmed to prevent colitis by inducing the expression of IL-10 in the colon." (PMID 34195297, 2021). "Only the CIR-rich IL-10-secreting splenic T cells had suppressive capacity as shown by in vivo models of colitis." (PMID 34177953, 2021). "The total histology scores for colitis, as well as the colonic mRNA expressions of IL-1β, IL-6, and IL-10 were higher after the sympathectomy, compared to the sham." (PMID 34884737, 2021). "Significantly, genetically or pharmacologically activating Hh signalling has been reported to ameliorate colitis by inducing the expression of IL-10 in Hh-responsive stromal cells, which subsequently increases the amount of CD4+Foxp3+ regulatory T cells." (PMID 34702800, 2021). "Over 90 percent of Citrine+ cells in DSS-induced colitis and IL10−/− colitis were vimentin+ fibroblasts." (PMID 33953267, 2021). "The progression of colitis in humanized Il10−/− mice was evaluated by serial fecal lipocalin-2 after human fecal gavage." (PMID 34050144, 2021). "A typical example is that the colitis developed in IL-10 mutant mice are refractory to anti-TNF-α therapy." (PMID 34746207, 2021). "Colitis in our model of experimental colitis in ex-GF 129SvEv IL10−/− mice humanized with pooled IBD fecal microbiota was more aggressive and occurred more rapidly than those of previous studies with SPF or conventionally raised C57BL/6 background mice." (PMID 34684567, 2021). "Consistent with DSS-induced colitis, Il10−/− mice colonized with A. pulmonis exhibited a significant shortened colon and developed more severe colitis after 3-week colonization compared to mice colonized with E. fergusonii or BHI." (PMID 34814945, 2021). "For instance, one study discovered a significant expansion of Bilophila wadsworthia and more severe inflammation in IL10−/− mice supplemented with taurocholate instead of glycocholate, which indicated the important role of taurine-derived sulfide in colitis." (PMID 34439208, 2021). "While we did not pursue the mechanism of the protection against colitis, the similarities in the splenic response at 4- and 8-dpi imply a common mode of action involving IL-4 and IL-10 signaling in the blockade of colitis, as we previously determined." (PMID 34451458, 2021). "Our results found that BL down-regulated the expressions of IL-1β, IL-6, and TNF-α inflammatory factors in the colon tissue of colitis mice and increased the expression levels of anti-inflammatory factors IL-10 and TGF-β." (PMID 33954162, 2021). "A dominant Th2 response causes lower IL-22 levels, consistent with our finding: PS23 FM upregulated the level of IL10 in the DSS-induced colitis mouse model to create a more anti-inflammatory environment, which inhibited IL22 expression." (PMID 34681392, 2021).
colitis (continued). "Administration of indole-3-pyruvic acid (I3Py) to mice with CD4+ T cell-induced colitis led to an increase in the amount of IL-10-producing T cells, while the number of Th1 cells in the mucosa was decreased, resulting in a reduction in colitis symptoms." (PMID 34073220, 2021). "Functionally, Tr1 cells suppress antigen-specific T-cell proliferation in an IL-10-dependent manner and are protective in the adoptive naïve T cell transfer model of colitis." (PMID 34421921, 2021). "Sampling should be performed over time, including early time points that precede the onset of colitis, and employing littermates (IL-10+/+ and IL-10–/–) that are co-housed." (PMID 34603258, 2021). "Studies have reported that TB supplementation can increase the levels of IL-10 in retroperitoneal adipose tissue and colitis+TBT mice, and the content of TGF-β is also increased by TB supplementation in experimental colitis." (PMID 33912175, 2021). "For example, Tregs from mice deficient in cytotoxic CTLA-4, IL-35, IL-10, or LAG-3 are unable to effectively suppress T cell proliferation and fail to prevent chronic T cell-mediated colitis in vivo." (PMID 32617076, 2020). "IL-10 levels were decreased in the TNBS-induced colitis group compared with the control group but increased after the administration of PF (20 mg/kg), PF-treated DCs or prednisone." (PMID 32472435, 2020). "In order to evaluate the relation of less studied IL-10 serum levels and colonic inflammation in UC patients, we included histological and endoscopic scores." (PMID 32695157, 2020). "B cells were previously shown to produce interleukin-10 (IL-10) and to have regulatory functions in autoimmune models of colitis, experimental autoimmune encephalitis (EAE), and arthritis (6, –, 8)." (PMID 32398312, 2020). "A recent study also suggests that butyrate is able to control the capacity of T cells by differentially regulating Th1 and Th17 cell differentiation and promoting IL-10 production in the induction of colitis." (PMID 33036205, 2020). "The success of PH46A in ameliorating the effects of in vivo activity in the DSS and IL-10−/− murine model of colitis has led to its potential as a therapeutic agent in IBD." (PMID 32301120, 2020). "In a similar study, we showed that this new recombinant strain can attenuate the severity of intestinal inflammation in acute TNBS-induced colitis by increasing the levels of the anti-inflammatory cytokine IL-10 and immunoglobulin sIgA20." (PMID 33208841, 2020). "In a recent work on a rat colitis model, it was demonstrated that the immunoregulatory impacts of locally injected MSCs from adipose results in a recovered expression of Foxp3 and IL-10 mRNA levels in mesenteric lymph nodes." (PMID 32256612, 2020). "In the murine IL-10 knockout model of colitis, treatment with the citrus flavonoid nobiletin resulted in a reduction of clinical colitis and a reduction of mast cell number and degranulation, which correlated positively with disease activity indexes." (PMID 32962285, 2020). "The development of spontaneous colitis in Il10-/- mice strongly depends on the microbiota composition." (PMID 33664727, 2020). "The concentration of IL-10 was lower in the experimental colitis model mice group compared with the normal control mice group, whereas was dramatically upregulated after treatment of QCHS (3, 6 and 12 g/kg) or SASP." (PMID 32967687, 2020). "Previous investigations revealed that antibiotics can significantly promote the development of colitis in IL10–/– mice by perturbing the gut microbiota, indicating that antibiotics reshape the intestinal microbiota and can affect host physiology and health." (PMID 32670220, 2020). "Treatment with rSj-Cys significantly reduced TNBS-induced experimental colitis in mice through upregulation of Treg cells and related cytokines IL-10 and TGF-β, and downregulation of pro-inflammatory cytokines TNF-α and IL-6 in the colon tissues of mice." (PMID 32423469, 2020).